MIR605 (microRNA 605)
Synonyms: hsa-mir-605; MIRN605; mir-605
Gene: MicroRNA gene on chromosome 10 (51,299,573 to 51,299,655, forward strand). Ensembl gene ENSG00000207813.
Gene Ontology:
Biological process: miRNA-mediated post-transcriptional gene silencing
Cellular component: RISC complex
Diseases named in the same sentence as MIR605 in open-access papers:
MIR605 is named in the same sentence as 1 disease in open-access papers, as found by Europe PMC text mining. Sharing a sentence is not in itself a finding about the gene and the disease. The quoted sentences say what the papers report.
cancer (1 paper, 2023). A tumor composed of atypical neoplastic, often pleomorphic cells that invade other tissues. "The rs2043556 (MIR605) variant has also been linked to the development of a variety of cancers, including breast and gastrointestinal cancer; it may affect the functionality of the MIR605 processing gene." (PMID 36901860, 2023). "The MDM2 gene is involved in different parts of the cancer signaling cascade, being a direct target of regulation by MIR605." (PMID 36901860, 2023).